BDNF (brain derived neurotrophic factor)
Diseases named in the same sentence as BDNF in open-access papers (continued):
Sharing a sentence is not in itself a finding about the gene and the disease.
depression (continued). "Brain-derived neurotrophic factor (BDNF) is a central regulator of plasticity and studies have shown that short-term SD results in upregulation of BDNF as well as having a short-term positive effect against depression." (PMID 40462346, 2025). "Clinical reports have demonstrated that low levels of brain‐derived neurotrophic factor (BDNF) may be present before the onset of stroke, which is prone to manifest as depression." (PMID 40994138, 2025). "The role of BDNF in depression pathophysiology is well established." (PMID 41226736, 2025). "BDNF also strengthens neuronal synaptic plasticity, i.e., the ability of synapses to change their strength in response to activity, enhancing learning and memory, and has therapeutic potential in depression and neurodegeneration." (PMID 41157245, 2025). "The results showed that noninvasive brain stimulation could effectively improve the sleep quality, structure, depression level and BDNF level of PSI patients, and it was also safe." (PMID 40608764, 2025). "Aerobic exercise may ameliorate depression and hippocampal neurogenesis and increase hippocampal BDNF expression in a rat model of PSD." (PMID 40361157, 2025). "However, among men with CP and depression, BDNF concentrations were lower (17.9 ng/mL ± 3.9) compared to their counterparts without depression (19.2 ng/mL ± 6.0)." (PMID 40222813, 2025). "The interplay between glutamate and BDNF may optimize glutamatergic signaling, reduce oxidative stress, and protect neurons, thereby improving mood disorders like depression." (PMID 39996878, 2025). "In non-depressed participants, women with severe pain showed lower BDNF concentrations than those without chronic pain, whereas in men with depression, both severe and interfering pain were linked to lower BDNF levels." (PMID 41002409, 2025). "BDNF was decreased in the serum and amygdala of patients with depression." (PMID 39962033, 2025). "In rats with CUMS induced depression, hippocampal BDNF levels decreased in the stress group." (PMID 40281288, 2025). "The decrease in BDNF not only affects neuronal survival and plasticity but may also exacerbate pain and depression-like behaviors through descending modulation, forming a vicious cycle." (PMID 41487490, 2025). "Genes including Oprm1 and BDNF demonstrated functional relevance in modulating neural activity and behavior, offering promising candidates for early diagnosis and individualized treatment of depression." (PMID 40656047, 2025). "Changes in BDNF levels in the CNS disrupt this signaling pathway, which could lead to several psychological disorders, including depression." (PMID 41373743, 2025). "Elevated PAI-1 levels, reduced tPA activity, and the decreased brain-derived neurotrophic factor (BDNF), influenced by coagulation and inflammation, may contribute to depression and its link to MI." (PMID 40282201, 2025). "In addition, it has been suggested that BDNF deficits are related to the pathogenesis of several neuronal disorders such as Parkinson’s, Huntington’s, Alzheimer’s, depression, chronic stress and anxiety." (PMID 41460391, 2025). "Notably, serum BDNF levels tend to decline with aging and in conditions such as depression and neurodegeneration, and after stroke." (PMID 40757562, 2025). "SSA therapy markedly enhanced the expression of p-CREB and BDNF, decreased the expression of Bax and Caspase-3, elevated the expression of Bcl-2, and inhibited the death of hippocampal neurons, therefore ameliorating depression-like behavior in PSD rats." (PMID 40458804, 2025). "Also, it has also been reported that BDNF acts as a transducer between antidepressants and changes in neurons to improve symptoms of depression." (PMID 41300755, 2025). "Chronic stress, a major precipitant of depression, further downregulates BDNF expression and signaling, particularly in the hippocampus, leading to neuronal atrophy, impaired synaptic plasticity, and decreased neurogenesis—hallmarks of depression." (PMID 40004867, 2025).
depression (continued). "Furthermore, iPSC-derived neural progenitor cells engineered to overexpress brain-derived neurotrophic factor (BDNF) have been shown to enhance neurogenesis and reverse depression-like behavior in rodent models exposed to chronic stress." (PMID 40943227, 2025). "These categories highlight the varied impacts of physical activity on BDNF levels and symptom management, particularly in chronic conditions, to better understand their contributions to improving symptoms such as fatigue, pain, and depression." (PMID 40002745, 2025). "The neurotrophic hypothesis emphasizes the role of brain-derived neurotrophic factor, a protein essential for neural development, maintenance, and survival in the development of depression." (PMID 40003622, 2025). "Furthermore, the long and short-term impacts of exercise on both depression and migraine suggest a role for endogenous opioids and neurotrophic factors (e.g. brain-derived neurotrophic factor, BDNF)." (PMID 40634879, 2025). "This study demonstrated lycopene could alleviate depression‐like behavior in chronic social defeat stress‐induced mice by promoting synaptic plasticity via the BDNF–TrkB pathway." (PMID 39844795, 2025). "Additionally, HE enhanced pro-BDNF and BDNF production, promoted hippocampal neurogenesis, improved behavior, and reduced symptoms of depression, anxiety, binge eating, and sleep disorders." (PMID 40959699, 2025). "While this idea remains underexplored, some studies suggest that BDNF could play a role in mediating improvements in conditions like depression, fatigue, and cognitive dysfunction." (PMID 40002745, 2025). "Altered BDNF signaling in these regions may contribute to the affective and cognitive symptoms of chronic pain, including anxiety, depression, and impaired emotional regulation." (PMID 40940732, 2025). "While CRP and BDNF are more accessible for extraction and detection, CRP reflects generalized systemic inflammatory without specificity for depression, and BDNF, although associated with neuroplasticity, lacks specificity across psychiatric disorders." (PMID 41425661, 2025). "Furthermore, we discovered that lycopene exerts its antidepressant effects by improving synaptic plasticity through the BDNF–TrkB pathway, which promotes the application of natural foods in depression treatment." (PMID 39844795, 2025). "This study aimed to investigate the effects of hesperidin (HSP-NPs) and quercetin (QUR-NPs) nanoparticles on oxidative stress markers, enzyme activities, brain-derived neurotrophic factor, and monoamine levels in the cortex and hippocampus of a reserpine-induced rat model of depression." (PMID 40522360, 2025). "Thus, in this cross-sectional study, we explored the potential relationship between peripheral BDNF levels and depression and anxiety symptoms in CUD." (PMID 40943216, 2025). "Serum BDNF levels are evaluated in the treatment of depression." (PMID 40281288, 2025). "Collectively, these genes contribute to diverse regulatory pathways, including neurotransmitter metabolism (Tph2), neurotrophic signaling (BDNF), metabolic regulation (Sucnr1), and ribosomal function (Rps26), supporting their multilayered regulatory roles in the development of depression." (PMID 40656047, 2025). "BDNF promotes neuroplasticity and synaptic adaptation critical for depression recovery." (PMID 41584756, 2025). "Likewise, other studies have seen that CBL increases the amount of BDNF in vitro, in animal models of epilepsy, and depression and in the serum of human patients with Alzheimer’s disease." (PMID 41460391, 2025). "The neurotrophic hypothesis of depression proposes that BDNF depletion contributes to mood dysregulation, and pharmacotherapy restores BDNF levels to those observed in non-depressed people." (PMID 40943216, 2025).
depression (continued). "Additionally, through a positive feedback mechanism, it further upregulates BDNF expression, improves mitochondrial function, and mediates the neuroplasticity regulation induced by exercise, alleviating depression." (PMID 40699781, 2025). "Similarly, in a rat depression model, three weeks of 15 Hz rTMS enhanced BDNF and ERK levels, with effects persisting two weeks beyond stimulation." (PMID 41440017, 2025). "In addition to the observed increase in serum BDNF and 5-HT levels in adolescents after exercise, the mechanisms through which exercise improves depression are multifaceted." (PMID 41477617, 2025). "Moreover, decreases in BDNF and PSA-NCAM, at least in the HPC, appear to be linked to stress conditions and depression, whereas chronic antidepressant treatments enhance the levels of both molecules." (PMID 40867109, 2025). "Similarly, other studies have highlighted the relationship between lower BDNF levels and depression recurrence and severity." (PMID 40904969, 2025). "The downregulation of BDNF expression can impair synaptic remodeling and neuronal connectivity, affect neural plasticity, exacerbate issues related to energy metabolism disorders, and subsequently mediate the development of depression." (PMID 40699781, 2025). "Consequently, many studies have found lower BDNF levels in patients with depression and anxiety disorders." (PMID 41153486, 2025). "In addition, BBR improves depression through the BDNF/CREB/eukaryotic elongation factor 2 pathway, with an onset of action 2 – 4 weeks faster than selective serotonin reuptake inhibitors." (PMID 41532063, 2025). "Two RCTs—one conducted in obese women with mild to moderate depressive symptoms and the other conducted in adults with obesity and mild depression —have already shown that ≥2000 IU cholecalciferol daily for 8–12 weeks increases serum BDNF levels (≈ +7%) and reduces BDI-II by 2–8 points." (PMID 40871684, 2025). "Most prominently, the neurotrophic hypothesis of depression implicates BDNF as a key mediator in the etiology of stress-related mood disorders." (PMID 39896238, 2025). "The serum CaMKII level was correlated with 5-HT, BDNF and could be used to predict depression in HVS patients." (PMID 41366912, 2025). "In patients with depression, plasma and serum BDNF levels are lower compared to healthy controls." (PMID 39798403, 2025). "The present study aims to assess and compare the serum concentrations of BDNF and IL-1β in individuals with depression, helping to identify potential biomarkers that could predict disease progression and responses to treatment." (PMID 40904969, 2025). "By focusing on these connections, this review offers insights into how BDNF may serve as a valuable biomarker in exercise-/PA-based interventions for fatigue, pain, depression, and sleep disturbance management across various conditions." (PMID 40002745, 2025). "The correlation between BDNF levels and treatment results could offer valuable insights for personalizing therapies and advancing the understanding of depression." (PMID 40423727, 2025). "In humans and rodents, decreasing hippocampal BDNF concentrations may be involved in the onset of depression and anxiety, concerning the fact that the hippocampus, as a part of the limbic system, is considered to be engaged in learning, mood, and anxiety." (PMID 41226297, 2025). "Building on these mechanistic insights, our findings demonstrate that BTS functions as a multi-target therapeutic agent that modulates obesity-depression comorbidity by mediating anti-inflammatory pathways, BDNF-NMDAR signaling, and serotonergic pathways in brain." (PMID 41244820, 2025). "Another significant theory, the neurotrophic hypothesis, implicates brain-derived neurotrophic factor (BDNF) in the development of depression." (PMID 40003622, 2025). "This suggests that rTMS may improve cognitive function, depression, psychiatric disorders, and Alzheimer’s disease in patients by upregulating serum BDNF and NGF levels." (PMID 40109842, 2025).
depression (continued). "Current studies suggest that exercise may alleviate depression through increased BDNF levels in brain regions such as the hippocampus and modulating neuroimmune responses in the brain." (PMID 41010394, 2025). "In addition, we aimed to compare BDNF peripheral levels between different severity categories of depression and anxiety symptoms in persons with CUD." (PMID 40943216, 2025). "Furthermore, the activation of estrogen-related receptor γ regulates BDNF expression in dopaminergic neurons and is seen to ameliorate depression-like behavior and enhance neurogenesis in the hippocampus via the upregulation of BDNF/TrkB signaling." (PMID 40141172, 2025). "Combining BDNF mimetics with established therapies, such as selective serotonin reuptake inhibitors (SSRIs) for depression or anti-Aβ treatment for AD, could enhance therapeutic outcomes." (PMID 40005159, 2025). "Notably, PA modulates hypothalamic-pituitary-adrenal (HPA) axis function, enhances brain-derived neurotrophic factor (BDNF) expression, and reduces systemic inflammation—mechanisms that are all implicated in the pathophysiology of depression and anxiety." (PMID 40927016, 2025). "Accumulating evidence e suggests that brain-derived neurotrophic factor (BDNF) may play a role in the development of depression." (PMID 40821018, 2025). "In the current study, the antidepressant‐like effects of NCUR resulted in a rise in BDNF and serotonin levels in serum, which could serve as a promising strategy for its use as a supplement along with other antidepressants during depression." (PMID 39972664, 2025). "Exercise-induced increases in BDNF also help regulate inflammatory pathways by reducing pro-inflammatory cytokines and fostering an anti-inflammatory environment, which is crucial in alleviating symptoms of fatigue and depression." (PMID 40002745, 2025). "Recent studies have proposed mechanistic links between IR and depression, including induction of central neuroinflammation, suppression of neurotrophic factor expression (e.g., brain-derived neurotrophic factor [BDNF]), and dysregulation of the hypothalamic–pituitary–adrenal (HPA) axis." (PMID 40551244, 2025). "In models of chronic stress-induced depression, escitalopram has demonstrated efficacy in mitigating oxidative damage, enhancing antioxidant defenses, and modulating brain-derived neurotrophic factor (BDNF) levels, thereby promoting neuronal healthy." (PMID 40600014, 2025). "According to the neuroplasticity hypothesis, BDNF levels decrease in depression, and this decrease is reversed with antidepressant treatment." (PMID 39968087, 2025). "However, blocking the expression of BDNF in the hippocampus can weaken the neuroplastic effects regulated by exercise, thereby inducing the occurrence and development of depression." (PMID 40699781, 2025). "Magnetic resonance imaging (MRI) also reveals damage to gray and white matter, indicating that BDNF may serve as a potential biomarker for depression." (PMID 40177374, 2025). "The upregulation of BDNF may explain improved memory outcomes, while elevated serotonin may explain the reduction in symptoms of anxiety and depression." (PMID 40108902, 2025). "However, it has also been demonstrated in many depression studies that BDNF can act as an upstream molecule of ERK, influencing its activation and downstream molecules." (PMID 39609371, 2025). "Decreased BDNF/TrkB agonist-dependent GR phosphorylation may contribute to comorbidity of MetS along with psychiatric disorders like anxiety and depression, making the BDNF/TrkB pathway a target for potential therapeutic recovery." (PMID 40362450, 2025). "The correct signalling of BDNF is crucial for preserving the emotional, cognitive and behavioural response of the brain to a changing environment, a flexibility that is compromised in people with depression." (PMID 40838256, 2025).
depression (continued). "Moreover, in the rat model of depression, Escitalopram elevated the BDNF levels, thereby reducing the oxidative stress in the hippocampus." (PMID 41302150, 2025). "On the other hand, boosting BDNF levels may enhance mood and cognitive function, making it a promising area of focus for developing new treatments for depression." (PMID 40821647, 2025). "Additionally, it acts as a vital function in the pathogenesis of depression by impacting inflammation, neurogenesis, circadian rhythm, and brain‐derived neurotrophic factor (BDNF), extracellular signal‐regulated kinase (ERK), and other signal pathways." (PMID 40237232, 2025). "Inhibition of BDNF by TNF-α may contribute to the pathophysiology of depression, as reduced levels of BDNF are commonly observed in depressed individuals." (PMID 40305200, 2025). "In addition to hippocampal BDNF, BDNF in several other brain regions including the medial prefrontal cortex (mPFC) and nucleus accumbens (NAc) play important roles in the pathogenesis of depression as well." (PMID 40356991, 2025). "In addition, exercise-induced IL-6 activates CREB via the PI3K/AKT pathway to decrease depressive disorder, primarily by activating BDNF signaling in the hippocampus." (PMID 40843259, 2025). "Baseline BDNF moderated response to exercise in MDD patients partially responding to antidepressants, with higher baseline levels linked to faster symptom improvement, even though overall BDNF levels did not correlate with depression improvement." (PMID 40665827, 2025). "Moreover, valsartan treatment significantly improved oxidative stress parameters (increased GSH, decreased MDA levels) and increased BDNF levels in the menopause-induced depression mouse model." (PMID 40943672, 2025). "BDNF expression is decreased in depressive disorders, and antidepressant treatments may restore its expression." (PMID 41373743, 2025). "Major Depressive Disorder (MDD) is the most prevalent manifestation of depression, including a reduction of Brain-Derived Neutrophic Factor (BDNF), which rules neurons survival; an increase in pro-inflammatory cytokines, and elevated levels of stress-related hormones." (PMID 39928205, 2025). "Furthermore, multiple studies have revealed that high glucocorticoid levels, such as corticosterone, a hallmark feature of chronic stress and HPA axis dysregulation in MDD, can reduce BDNF production, inhibiting adult hippocampal neurogenesis in depression." (PMID 41465304, 2025). "In addition, BDNF has been studied in the past as part of the mechanism of vitamin D’s effect on depression, but the pathways of specific mechanisms, such as the specific signaling involved, have not been determined." (PMID 39135986, 2024). "It is well‐known that some probiotics, strains like Bifidobacterium adolescentis and Lactobacillus reuteri, hold promise in averting anxiety/depression via inhibiting infiltration of Iba1+ and LPS+/CD11b + cells (activated microglia) into the hippocampus and inducing hippocampal BDNF expression." (PMID 39619956, 2024). "Neither serum NfL nor BDNF levels can serve as markers of depression risk in the dialysis population." (PMID 38255209, 2024). "There are various mechanisms, such as reduced inflammation, stress reduction, improved sleep, social interaction that have been reported about the effect that regular exercise has on depression related behaviors, as well as the increase in brain-derived neurotrophic factor, and serum testosterone." (PMID 39334051, 2024). "In conclusion, our study demonstrated that estradiol withdrawal elicited a depression- and anxiety-like state in rats and downregulated the BDNF/β-catenin expression in the IL, which could be reversed with ALLO supplementation." (PMID 38743109, 2024). "Given that BDNF expression may help mitigate the onset and progression of depression, activating the FNDC5/irisin-BDNF axis in the brain may offer a promising therapeutic approach for depression." (PMID 39484160, 2024).